NAP1L1 (nucleosome assembly protein 1 like 1)
Diseases named in the same sentence as NAP1L1 in open-access papers (continued):
Sharing a sentence is not in itself a finding about the gene and the disease.
tumor (continued). "In recent studies, NAP1L1 has been shown as a promoter of tumor pathogenesis." (PMID 34368121, 2021). "Furthermore, higher NAP1L1 expression in tumor cells predicted poorer overall survival for TNM stage I-II patients." (PMID 31516385, 2019). "Here, we found that NAP1L1 expression was significantly upregulated in HCC as compared to the adjacent non-tumor hepatocytes, and high NAP1L1 expression was significantly associated with aggressive clinicopathologic features (i.e., serum AFP levels, larger tumor size and late clinical stage)." (PMID 31516385, 2019). "The findings of our present study suggested that the measurement of NAP1L1 expression in tumor cells could identify worse prognoses among early stage HCC patients." (PMID 31516385, 2019). "Blood samples demonstrated a lower chromogranin A (CgA) serum expression in mice which had been injected with NAP1L1-knockdown cells (p < 0.05) suggesting that CgA may, as in humans, be a marker of tumor burden." (PMID 25071868, 2014). "We next examined whether NAP1L1-silencing reduced tumor formation in an orthotopic pNEN mouse model." (PMID 25071868, 2014). "NAP1L1 expression was also positively correlated with tumor size (Spearman’s r = 0.4, p < 0.05)." (PMID 25071868, 2014). "Methylation, through a NAP1L1-complex, is therefore a novel mechanism for p57Kip2 transcriptional control that may be applicable to other neoplasia." (PMID 25071868, 2014). "Violin plots effectively illustrated the expression levels of these regulatory modules among tumor subpopulations, with C2 MKI67+ TCs exhibiting the highest expression in M3, succeeded by C0 NAP1L1+ TCs." (PMID 40842994, 2025). "Compared with the Ctrl or Ctrl+Sh-NC group, tumor tissues derived from the HG or HG + Sh-NC group exhibited increased positivity for Pin1, BRD4, NAP1L1, PCNA, and MMP9, and reduced positivity for P21." (PMID 35461311, 2022). "NAP1L1 is a critical member of the Nucleosome Assembly Protein (NAP) family and has been widely portrayed in various tumor progressions." (PMID 35664324, 2022). "Immunohistochemical analysis of NAP1L1 was performed in tissue microarrays (TMA) containing 90 paired HCC samples and adjacent non-tumor tissues of human HCC, and cell staining was scored." (PMID 34368121, 2021). "Features associated with the survival in univariate Cox regression analysis were tumor scale (0.031), HER-2 (P = 0.014), NAP1L1 expression (P = 0.001), and PR (P = 0.039)." (PMID 34774047, 2021). "Our results are similar to other reports of NAP1L1 in HCC cancer, indicating that NAP1L1 is a tumor promoter participating in HCC pathogenesis." (PMID 34368121, 2021). "According to the analysis of Clinical Proteomic Tumor Analysis Consortium (CPTAC) database, NAP1L1 protein was upregulated." (PMID 34774047, 2021). "CDKN2B-AS1 has been reported promotes tumor growth and metastasis of HCC by targeting let-7c-5p/NAP1L1 axis." (PMID 32611831, 2020). "These tumours also exhibited a decrease in KRAS, NAP1L1, and ETS1 expression in 786-O/miR-532-5p cells, as assessed by IHC." (PMID 30082686, 2018). "Upregulated NAP1L1 increases the expression of the cell cycle protein cyclin D1 (CCND1) by recruiting heparin-binding growth factor (HDGF) and interacting with c-Jun, thereby enhancing the proliferation of HCC cells and promoting tumour progression." (PMID 38538582, 2024). "Knockdown of NAP1L1 promoted the ubiquitin-mediated degradation of BIRC2 through the ubiquitin–protein junction of UBR4, which in turn inhibited the proliferation and apoptotic escape of HCC cells and exerted anti-tumour effects." (PMID 38538582, 2024). "Upregulated NAP1L1 plays a pro-tumorigenic role by recruiting HDGF to interact with c-Jun, thereby upregulating the expression of CCND1 and promoting the proliferation of tumour cells." (PMID 38538582, 2024). "NAP1L1 expression was significantly higher in tumor tissues compared to the adjacent non-tumor tissues (p < 0.05, right)." (PMID 31516385, 2019).
tumor (continued). "NAP1L1 expression was significantly upregulated in tumor tissues as compared to adjacent non-tumor tissues." (PMID 31516385, 2019). "In the preliminary experiment, IHC staining of the HCC specimens showed clear and distinguishable cytoplasm staining for NAP1L1 in tumor tissues, but negative staining in adjacent hepatocytes (left)." (PMID 31516385, 2019). "Patients with positive NAP1L1 expression had a poorer surgical prognosis than those with negative NAP1L1 expression in tumor cells (p < 0.001)." (PMID 31516385, 2019). "Of the 85 patients at stage III–IV, the prognosis of patients with NAP1L1 expression in tumor cells was poorer than that of patients with negative NAP1L1 expression in tumor cells (p < 0.001)." (PMID 31516385, 2019). "Taken together, the cross-talk between miR-532-5p, KRAS, NAP1L1, and EST1 established a bridge between miR-532-5p and the MAPK-signalling pathway, demonstrating that miRNAs and their target genes participate in the development and progression of tumours." (PMID 30082686, 2018). "As p57Kip2 (CDKN1C), a negative regulator of proliferation and a tumor suppressor, is controlled by members of the NAP1 family, we tested the hypothesis that NAP1L1 may have a mechanistic role in regulating pancreatic NEN proliferation through regulation of p57Kip2." (PMID 25071868, 2014).
cancer (21 papers, 2008 to 2024). A tumor composed of atypical neoplastic, often pleomorphic cells that invade other tissues. "Recently, a growing body of evidence has indicated that NAP1L1 is closely linked to cancer development." (PMID 37593048, 2023). "Nucleosome assembly protein 1 like 1 (NAP1L1) is regarded as a hallmark of malignant tumors." (PMID 34959221, 2021). "Many studies have found that NAP1L1 is strongly expressed in tumors, highlighting its potential role in human cancer." (PMID 37770914, 2023). "In the last two decades, extensive studies show that NAP1L1 is an important regulator, critical for various biological processes in multiple cancer types." (PMID 34959221, 2021). "The HDGF cDNA plasmid was transfected to NAP1L1-suppressing cells, to explore the role of HDGF in NAP1L1-mediated pathogenesis of HCC cancer." (PMID 34368121, 2021). "Mechanistically, circDCAF8 plays the cancer-promoting role through the miR-217/NAP1L1 axis." (PMID 38816735, 2024). "Previous work has indicated that NAP1L1 is a potential oncogene in many cancers." (PMID 37593048, 2023). "Few researchers have previously studied NAP1L1 expression in cancer cell lines or tissues." (PMID 32850460, 2020). "This turns NAP1L1 into a promising target for anti-cancer therapy." (PMID 25071868, 2014). "Nucleosome assembly protein 1-like 1 (NAP1L1) was downregulated in all carcinoma groups, especially carcinoma luminal A. NAP1L1 is suggested to have an oncogenic role in several tumors based on its overexpression." (PMID 39000458, 2024). "Two additional NAGs of interest, namely NAP1L1 and SRFS2 (medium confidence = 0.400) were also included in the analysis due to their involvement in carcinogenesis and cancer metastasis." (PMID 35682908, 2022). "In a separate cohort of 75 CRC patients, we found a strong correlation between NAP1L1 nuclear expression and overall survival in those patients who had stage III and IV cancers." (PMID 32850460, 2020). "We assessed the expression of NAP1L1 firstly in mRNA from CRC tissues and matched normal mucosa from 18 patients supplied by the Wales Cancer Bank." (PMID 32850460, 2020). "We also found that the enrichment score of RSF1 + Macro-C1, NAP1L1 + Macro-C2, and DEK + Macro-C3 clusters have a positive correlation with Cancer immunity cycles score and immunoregulation-related pathways score which indicated a high activity level of all cancer immunity steps." (PMID 38057779, 2023).
infection (2 papers, 2016 to 2022). The state of being infected such as from the introduction of a foreign agent such as serum, vaccine, antigenic substance or organism. "Since NAP1L1 helps in assembling the nucleosome on the replicating DNA, we wanted to determine the consequence of NAP1L1 depletion on the maintenance of TR-containing plasmid by determining the plasmid levels seven days post-infection." (PMID 27599637, 2016). "NAP1L1-depleted or control HEK 293L cells were transfected with TR plasmid along with LANA expression vector for the isolation of nuclei 4 days post-infection." (PMID 27599637, 2016).
NAP1L1 also shares sentences with these, for which no sentence is quoted: glioblastoma (3 papers); neuroendocrine neoplasm (2); pancreatic cancer (2); small-intestinal carcinoid (2); viral infection (2); Alzheimer disease (1); carcinoid of the (1); cardiac disease (1); diabetics (1); head and neck squamous cell carcinoma (1); latent infection (1); malignant adenocarcinoma (1); Minor Salivary Gland Tumors (1); myocardial infarction (1); myopia (1); nasopharyngeal carcinoma (1); neuroendocrine carcinoma (1); Obesity (1); osteosarcoma (1); primary effusion lymphoma (1); psychiatric disorder (1).